CEP57L1 (centrosomal protein 57 like 1)
Description:
Centrosomal protein which may be required for microtubule attachment to centrosomes.
Synonyms: Cep57R; C6orf182; bA487F23.2; MGC21731
Tractability: PROTAC: ubiquitination databases record sites on it.
Gene: Protein-coding gene on chromosome 6 (109,095,105 to 109,174,418, forward strand). Ensembl gene ENSG00000183137.
Subcellular location: Cytoplasm, cytoskeleton, microtubule organizing center, centrosome
Gene Ontology:
Molecular function: identical protein binding; protein binding; microtubule binding; gamma-tubulin binding
Cellular component: centrosome
Genetic constraint (gnomAD): Loss-of-function variants: 17 observed, 26.88 expected, observed/expected ratio (o/e) 0.63, 90% interval 0.43 to 0.95. The upper end of that interval is the gene's LOEUF score, 0.95, which puts it in group 4 of 6, group 1 being the genes least tolerant of losing a copy. Missense variants: 232 observed, 302.65 expected, observed/expected ratio (o/e) 0.77, 90% interval 0.69 to 0.86. Synonymous variants: 78 observed, 94.01 expected, observed/expected ratio (o/e) 0.83, 90% interval 0.69 to 1.
Homologues: Orthologues: chimpanzee CEP57L1 (99% identical), macaque CEP57L1 (97% identical), pig CEP57L1 (85% identical), dog CEP57L1 (83% identical), guinea pig CEP57L1 (80% identical), rabbit CEP57L1 (80% identical), mouse Cep57l1 (69% identical), rat Cep57l1 (66% identical), tropical clawed frog cep57l1 (41% identical), zebrafish cep57l1 (37% identical). Paralogues in human: CEP57 (32% identical).
Diseases named in the same sentence as CEP57L1 in open-access papers:
CEP57L1 is named in the same sentence as 4 diseases in open-access papers, as found by Europe PMC text mining. Sharing a sentence is not in itself a finding about the gene and the disease. The quoted sentences say what the papers report.
colorectal cancer (1 paper, 2025). A primary or metastatic malignant neoplasm that affects the colon or rectum. "Collectively, these results are consistent with our view that CA favors the metastasis of colorectal cancer via the KLF5–KLHL13–CUL13 signaling pathway, which results in insufficient degradation and therefore increment in CEP57L1." (PMID 41443421, 2025).
diabetes (1 paper, 2025). "Cancer tissues had lower levels of KLF5, KLHL13, and CUL3 but higher levels of CEP57L1 than paracarcinoma counterparts, which was exaggerated by the presence of diabetes." (PMID 41443421, 2025). "In a cohort of cancer patients, KLF5, KLHL13, and CUL3 levels were lower, but CA and CEP57L1 were higher in cancer tissues, compared with noncancerous counterparts, which were more obvious in those with diabetes." (PMID 41443421, 2025). "Importantly, our data reveal that the AGE–KLF5–KLHL13–CUL3 axis specifically regulates CEP57L1 without affecting its paralog CEP57, highlighting a nonredundant and pathway-specific role for CEP57L1 in this diabetic cancer context." (PMID 41443421, 2025).
cancer (1 paper, 2025). A tumor composed of atypical neoplastic, often pleomorphic cells that invade other tissues. "Next, we moved to test whether AGEs could promote cancer cell metastasis via CA in the mouse model, for which we compared the metastasis potential of wildtype cells and those with knockdown of CEP57L1 (CA inhibition)." (PMID 41443421, 2025). "Importantly, AGEs promoted CEP57L1-dependent metastasis of the cancer cells in a mouse model." (PMID 41443421, 2025). "The expression of CEP57L1 was statistically higher in cancer patients, and it did exhibit a negative correlation with the overall survival of cancer patients (." (PMID 41443421, 2025). "Consistent with the functional role of CEP57L1, its expression was higher in cancer tissues than paracarcinoma counterparts, irrespective of cell type." (PMID 41443421, 2025).
tumor (1 paper, 2025). "The level of CEP57L1 in tumor and paracarcinoma tissues in mice inoculated with CEP57L1 knockdown cells without AGE treatment was not quantified because of the shortage of metastatic tissues." (PMID 41443421, 2025).